FANCI (FA complementation group I)
Diseases named in the same sentence as FANCI in open-access papers (continued):
Sharing a sentence is not in itself a finding about the gene and the disease.
Fanconi anemia (continued). "The associations involving DNA double-strand break repair pathway and Fanconi anemia, in particular, were also evident when examining key individual genes, including BRCA1, BRCA2, FANCD2, FANCI, and RAD51." (PMID 31610796, 2019). "The primary function of the UBE2T ubiquitin conjugase is in the monoubiquitination of the FANCI-FANCD2 heterodimer, a central step in the Fanconi anemia (FA) pathway." (PMID 30715513, 2019). "This suggests that mismatch repair pathway-coupled O6-alkylguanine-mediated DSBs during DNA replication activates the Fanconi anemia core complex and leads to the monoubiquitination of FANCD2 and FANCI." (PMID 27486975, 2016). "FANCL is the RING E3 subunit of the Fanconi anaemia complex, which functions with the E2 UBE2T to mono-ubiquitylate FANCD2 and FANCI following interstrand cross-link (ICL) detection, and is therefore crucial for ICL repair." (PMID 25833379, 2015). "Generally, when an ICL blocks the replication machinery, a protein complex termed as the Fanconi anemia core complex is recruited to stalled replication forks and monoubiquitinates another two Fanconi anemia proteins FANCD2 and FANCI." (PMID 24170812, 2014). "The Fanconi anemia (FA) core complex promotes the tolerance/repair of DNA damage at stalled replication forks by catalyzing the monoubiquitination of FANCD2 and FANCI." (PMID 18851838, 2008). "In our study, moderately increased BC risk was defined for mutations in the Fanconi anemia genes FANCC (OR = 2.4) and FANCI (OR = 4.3), but not for FANCM (OR = 0.6), although the difference was not significant." (PMID 39684352, 2024). "This approach revealed the FANCI (Fanconi anemia pathway) as a partner of FANCD2 (ferroptosis negative regulator, up) in COAD." (PMID 33670487, 2021). "Relevant to the adaptation of TRD to arid conditions, ten selected genes (including SLX4, FANCF, FANCG, FANCI, ATR, and POLH) were related to the fanconi anemia pathway (bta03460, p < 0.01) involved in DNA repair, DNA replication fork stability, and other cellular processes." (PMID 33072165, 2020). "Additionally, we found 7 monoallelic pathogenic variants (2%, 7/327) in 6 genes (besides BRCA1/2) of the interstrand crosslink DNA repair Fanconi anemia pathway (FANCB, FANCC, FANCF, FANCI, FANCL, FANCM) and 1 in RAD51C, a Fanconi-like phenotype gene." (PMID 30262796, 2018). "Interestingly, genes from the Fanconi Anemia pathway FANCA, FANCI, FANCD1 (also known as BRCA2) were enriched in radiosensitive GSCs compared to radioresistant GSCs." (PMID 30282933, 2018). "In our efforts to understand the molecular basis of treatment response in advanced cervical cancer, besides the BRCA pathway, we also found the fanconi anemia (FA) complementation group, FANCD2, FANCL, FANCM, FANCJ/BRIP1/BACH and FANCI, to be involved in intrinsic resistance to chemo-radiotherapy." (PMID 24708616, 2014). "Moreover, monoubiquitinated FANCD2 (ub-FANCD2) is required for FANCI monoubiquitination (ub-FANCI) and recruitment of Breast Cancer 1 (BRCA1), Fanconi Anemia Complementation Group J (FANCJ), and Fanconi Anemia Complementation Group N (FANCN), to form damage-induced foci on chromatin 29,30." (PMID 33029090, 2020). "Although deficiency of each gene shows similar clinical and cellular phenotypes, ∼60% of Fanconi anemia patients presented defective FANCA, indicating that this protein may have additional biological functions beyond the canonical pathway through FANCI-FANCD2 monoubiquitination." (PMID 24170812, 2014).
breast carcinoma (23 papers, 2013 to 2025). "In breast cancer elevated FANCI expression was associated with increased proliferation, while FANCI inhibition has also been shown to sensitize breast cancer cells to the PARP inhibitor in the absence of BRCA mutations." (PMID 39767562, 2024). "For example, the FANCA and FANCI genes which have been implicated in breast cancer, had pathogenic variants detected in both breast cancer patients and individuals with hereditary breast and ovarian cancer (HBOC)." (PMID 37461096, 2023). "The FANCI missense variant M525V (rs144908351) is recorded as uncertain significance and was previously reported in ovarian and breast cancer patients." (PMID 34573422, 2021). "Furthermore, FANCI mutations were found that mainly involved in breast cancer and ovarian cancer." (PMID 36428813, 2022). "This contrasts with MM1 domain mutations identified in non-BRCA1/2 breast cancer families, which show the opposite pattern-disrupted FANCD2:FANCI monoubiquitination but intact ATPase activity." (PMID 40447800, 2025). "Among breast cancer subtypes, the top eight mutational rates were MAD2L2/FANCV (37.5%), FANCI (32%), ATR (32%), FAAP20 (30%), FAAP100 (28%), SLX4 (27%), FANCT (27%), and BRIP1 (26%) in breast invasive carcinoma NOS." (PMID 39421870, 2024). "PRMT5 expression was moderately to strongly correlated (Pearson score ≥ 0.4) with established DDR genes such as BRCA1, BRCA2, RAD51, RAD51D, RAD51AP1, FANCA, and FANCI across 125 ovarian and breast cancer cell lines." (PMID 37861290, 2023). "Pathogenic variants in the FANCI, MET and STK11 have been reported in association with breast cancer." (PMID 37277882, 2023). "In ethnic-specific analyses of overall breast cancer only one additional SNP (in FANCI) met our criteria (p<3.9×10−7) of global significance." (PMID 23555315, 2013). "Finally, the increase in expression of the genes CCNE1, FANCI, RFC4, CDC6, and YWHAZ associated with poor prognosis in luminal A breast cancer (OS, HR:2.54, CI 1.69–3.82, log rank p = 3.6 × 10−6; RFS, HR:1.84, CI 1.53–2.22, log rank p = 6.5 × 10−11)." (PMID 33925616, 2021). "FANCI has also been reported to regulate breast cancer survival." (PMID 33868991, 2021). "The FA genes we identified as DEGs; CENPX, FAAP24, FANCD2, FANCI, UBE2T and FANCA are all overexpressed in breast cancer." (PMID 33662042, 2021). "Next, the expression level of two FA/BRCA genes, FANCD2 and FANCI, was confirmed by qPCR and western blot in PAK1 depleted human breast cancer cells." (PMID 27740936, 2016). "Finally, the results of a TCGA analysis we performed showed that PAK1 overexpression in human breast cancer samples correlates with the expression of most FA/BRCA genes, particularly with FANCI." (PMID 27740936, 2016). "The expression of two FA genes, FANCD2 and FANCI, was confirmed by qPCR and western blot in PAK1 depleted human breast cancer cells with or without PAK1 amplification and/or overexpression." (PMID 27740936, 2016).
ovarian carcinoma (13 papers, 2015 to 2024). A malignant neoplasm originating from the surface ovarian epithelium. "FANCI was recently identified as a new candidate ovarian cancer (OC)-predisposing gene from the genetic analysis of carriers of FANCI c.1813C>T; p.L605F in OC families." (PMID 36833203, 2023). "Previously, FANCI has been shown to associate with carcinogenesis, which knock down the FANCI expression promotes DNA damage and makes ovarian cancer cells more sensitive to chemotherapy." (PMID 37168687, 2023). "Based on genetic research of FANCI c.1813C > T carriers; p.L605F in OC families, FANCI is deemed a new putative gene for ovarian cancer (OC)." (PMID 39767562, 2024). "As shown in the literature, mainly polymorphisms of FANCI and BRIP-1 genes and their association with ovarian cancer have been studied." (PMID 39767562, 2024). "The top 10 genes with most deleterious mutations in the Chinese ovarian cancer population were MC1R (12%), MLH1 (9%), PRKDC (8%), KIF1B (8%), FANCM (7%), FANCI (6%), PRSS1 (6%), SDHA (6%), BRCA2 (6%), and CFTR (5%)." (PMID 38817903, 2024). "The aim of this study was to evaluate the expression of BRIP-1 (FANCJ) and FANCI proteins in ovarian cancer tissue and to assess these expressions in differentiating the described clinical features." (PMID 39767562, 2024). "It was also observed in ovarian cancer, where FANCI silencing promoted DNA damage and sensitized cancer cells to carboplatin." (PMID 39767562, 2024). "Both the literature data and the results presented in this article indicate that FANCI and BRIP-1 proteins are associated with ovarian cancer." (PMID 39767562, 2024). "In another study, the upregulation of Polθ and its positive correlation with expression of many DNA repair genes including TOPBP1, BLM, RAD54L, FANCI, BRCA1, FANCD2, ATAD5 was reported in HR-deficient epithelial ovarian cancer cells." (PMID 34762643, 2021). "Immunohistochemical evaluation of FANCI and BRIP-1 (FANCJ) protein expression in ovarian cancer tissue samples was performed." (PMID 39767562, 2024). "On the other hand, the study we present is one of the first to present immunohistochemical evaluation of tissue expression of FANCI and BRIP-1 in ovarian cancer tissue." (PMID 39767562, 2024). "This study shows that FANCI protein is a marker associated with lower FIGO stage and histologically high-grade cancer in a group of all ovarian cancers and in non-HGSOC." (PMID 39767562, 2024).
anemia (10 papers, 2016 to 2025). A reduction in the number of red blood cells, the amount of hemoglobin, and/or the volume of packed red blood cells. "However, we identified three novel variants in the Fanconi anemia, complementation group I gene (FANCI) in three patients (patients 9, 15, and 16), and one novel variant in the RAD54 homolog B gene (RAD54B) in one melanoma patient (patient 14)." (PMID 39795882, 2024). "A disorder affecting all bone marrow elements that may result to anemia, leukopenia and thrombopenia could be caused by FANCI mutation." (PMID 32271791, 2020). "For example, ubiquitination promotes the phosphorylation of FANCI S/TQ cluster and activates the Fanconi Anemia I/D2 complex." (PMID 37028761, 2023). "Interestingly, we found that 10 of 11 patients with lymphoma and another solid tumor harbored germline mutations in Fanconi anemia complementation group (FANC) genes, including FANCI, FANCA, FANCG, FANCL, FANCD1, FANCF, FANCJ, and FANCS." (PMID 37546421, 2023). "Thus, similar to a recent report analyzing Fanconi anemia complementation group I (FANCI), ATR-mediated WRN phosphorylation is somehow involved in the suppression of dormant origin firing upon replication stress." (PMID 26695548, 2016). "FANCI is a member of the Fanconi anaemia complementation (FANC) gene family." (PMID 26798408, 2016). "Notably, proteins decreased only after both combination treatments include proteins involved in the DNA damage response (DDR) like BRAT1, Fanconi Anemia Complementation Group I (FANCI) and CHEK1, indicating that the cells might be more prone to DNA damage." (PMID 30871073, 2019). "Our triplet links also include 60 genes known to be recurrently mutated or overexpressed in medulloblastoma, including OTX2, MYCN, the Fanconi anemia proteins FANCA and FANCI, and others." (PMID 41279093, 2025). "More recently, it has been reported that in lung cancer cells, RPS27L physically binds Fanconi anemia group D2 (FANCD2) and Fanconi anemia group I (FANCI), two proteins involved in DNA damage and repair." (PMID 34071057, 2021).
lung adenocarcinoma (8 papers, 2016 to 2025). A carcinoma that arises from the lung and is characterized by the presence of malignant glandular epithelial cells. "High expression of FANCI has been associated with a poor prognosis in cancer, as proved in lung adenocarcinoma, as it promotes tumor growth by suppressing M1 macrophages, which play an anti-tumor role in the immune response." (PMID 40415137, 2025). "FANCI mRNA and protein were both found to be overexpressed in lung adenocarcinoma tumor tissues compared with adjacent normal tissues." (PMID 33868991, 2021). "The high FANCI expression level may boost up tumor growth in lung adenocarcinoma by inhibiting M1 macrophages." (PMID 38077326, 2023). "Regarding lung adenocarcinoma (LUAD), FANCI demonstrates positive correlations with cell cycle regulation, DNA damage response, DNA repair, cellular proliferation, and invasion, and a negative correlation with inflammation." (PMID 40417238, 2025). "FANCI is a key protein in DNA repair and ribosome biogenesis and cooperates with IMPDH2 to promote cell proliferation of (lung adenocarcinoma) LUAD." (PMID 35846349, 2022). "In addition, there was a significant difference in FANCI expression between Brain Lower Grade Glioma (LGG), LIHC, Lung adenocarcinoma (LUAD), and Mesothelioma (MESO), which a p-value < 0.01." (PMID 37324186, 2023).
cervical cancer (6 papers, 2014 to 2025). A primary or metastatic malignant neoplasm involving the cervix. "High lnc-FANCI-2 and low MCAM levels in cervical cancer tissues were found to be associated with patients’ survival." (PMID 40878909, 2025). "Both lnc-FANCI-2 and FANCI are upregulated simultaneously in neoplastic cervical lesions and cervical cancer by HR-HPV infections." (PMID 40878909, 2025). "FANCI expression was upregulated in cervical cancer, and upregulated FANCI predicts poor prognosis in patients." (PMID 38077326, 2023).
glioma (6 papers, 2021 to 2026). A benign or malignant brain and spinal cord tumor that arises from glial cells (astrocytes, oligodendrocytes, ependymal cells). "In glioma, FANCI is positively linked to cell cycle activities, cellular proliferation, DNA repair, epithelial-mesenchymal transition (EMT), and invasive behavior." (PMID 40417238, 2025). "When exposed to cisplatin, all three cell types exhibited robust monoubiquitination of FANCI and FANCD2, demonstrating that FA pathway activation is a conserved response in glioma." (PMID 41486508, 2026). "Additionally, the mRNA expression levels of MST4/STK26, USP14, and ALKBH5 were positively correlated with ALKBH5 target genes, including FANCD2, FANCI, MKI67, and RAD51 within the TCGA and CGGA glioma datasets." (PMID 39990235, 2025).
melanoma (6 papers, 2021 to 2025). A malignant, usually aggressive tumor composed of atypical, neoplastic melanocytes. "Variants of FANCI may enhance DNA damage accumulation in melanoma cells, which may promote more aggressive cancer characteristics." (PMID 39795882, 2024). "In the context of melanoma (MEL), FANCI is positively associated with cell cycle regulation, cellular proliferation, DNA repair mechanisms, and DNA damage, while it is inversely associated with inflammatory responses." (PMID 40417238, 2025). "The germline variants of BRCA2, POLE, WRN, FANCI, PALB2, and RAD54B genes, involved in DNS repair mechanisms, have been implicated in rendering melanoma patients more susceptible to tumor progression and affecting their response to treatments." (PMID 39795882, 2024). "Additionally, variants of FANCI, PALB2, and RAD54B are associated with altered survival outcomes in melanoma patients." (PMID 39795882, 2024). "Here, our aim was to investigate whether patients in the Hungarian melanoma cohort (n = 17) with increased risk carry any pathogenic or likely pathogenic germline variants of the BRCA2, POLE, WRN, FANCI, PALB2, and RAD54B genes associated with melanoma survival and response to therapy." (PMID 39795882, 2024).
colon cancer (4 papers, 2019 to 2023). "HCT116 is a colon cancer cell line routinely employed to evaluate the ubiquitination and chromatin localization of FANCI in the evaluation of the ICL repair pathway." (PMID 31240132, 2019). "Chen and others (2020) have indicated FANCI and ZWILCH as crucial genes in colon cancer progression and proposed them as potential targets for colon cancer treatment." (PMID 37189849, 2023). "Our results identified FANCI and ZWILCH as critical target genes of colon cancer, suggesting that they might provide a potential pathway for the treatment and intervention of colon cancer." (PMID 32582275, 2020).
colorectal cancer (4 papers, 2021 to 2023). A primary or metastatic malignant neoplasm that affects the colon or rectum. "The role of FANCI in other cancer types remains to be determined, though there have been reports of FANCI variant carriers in a variety of cancer types such as prostate cancer, sarcoma, malignant pleural mesothelioma, acute myeloid leukaemia, head and neck carcinoma, and colorectal cancer." (PMID 34861889, 2021). "besides, in colorectal cancer cell lines, SW620, SW480, HCT116, LS174T cells showed much higher expression of FANCI compared with FHC cells." (PMID 37324186, 2023).
hepatocellular carcinoma (4 papers, 2018 to 2025). A malignant tumor that arises from hepatocytes. "In conclusion, we investigated the capabilities of FANCI as a prognostic and therapeutical biomarker in live hepatocellular carcinoma." (PMID 37324186, 2023). "For the different histological types, results indicated that most liver cancers belonged to hepatocellular carcinoma, which had higher expression of FANCI than normal tissue." (PMID 37324186, 2023). "It has also been reported that PRC1 controls the expression and function of wrrag such as FANCI, SPC25, KIF11, and KIF23 via Wnt signaling in hepatocellular carcinoma (HCC)." (PMID 40400636, 2025).